RN7SL624P (RNA, 7SL, cytoplasmic 624, pseudogene)
Gene: Miscellaneous RNA gene on chromosome 17 (2,199,762 to 2,200,039, forward strand). Ensembl gene ENSG00000265777.
Homologues: Orthologues: chimpanzee Metazoa_SRP (98% identical), macaque Metazoa_SRP (78% identical). Paralogues in human: RN7SL440P (81% identical), RN7SL524P (80% identical), Metazoa_SRP (80% identical), RN7SL602P (79% identical), Metazoa_SRP (78% identical), RN7SL718P (78% identical), Metazoa_SRP (77% identical), Metazoa_SRP (76% identical), Metazoa_SRP (75% identical), RN7SL525P (75% identical), Metazoa_SRP (74% identical), RN7SL121P (73% identical), and 707 more.